CD4 (CD4 molecule)
Diseases named in the same sentence as CD4 in open-access papers (continued):
Sharing a sentence is not in itself a finding about the gene and the disease.
infection (continued). "However, although we didn't detect integrated HIV DNA in myeloid cells 24 h post-infection, we detected integrated HIV DNA in CD4+ T cells, consistent with productive infection in CD4 T cells but not in myeloid cells at this early timepoint." (PMID 30532754, 2018). "Moreover, the levels of KCTD9 mRNA was increased in hepatic NK cells, CD4+ T cells and CD8+ T cells by 48 h of infection, without significant difference in hepatocytes." (PMID 29940856, 2018). "Adoptive transfer of infection-derived CD4+ T cells, but not innate or CD8+ T cells, into normally resistant IFN-γ−/− mice (infected with PbA) promoted the development of ECM by active secretion of IFN-γ, implicating cytokine derived from CD4+ T cells in ECM." (PMID 30250468, 2018). "Interestingly, mice models of hMPV-infection show that CD8+ T cells, but not CD4+ T cells nor neutralizing antibodies, are involved in the protection from reinfection." (PMID 30405642, 2018). "Furthermore, CD4 and not CD8 cells were shown to participate in elimination of B. microti in mouse infection model." (PMID 29445365, 2018). "Flow cytometry analysis revealed that, although conventional CD4+ T cells gradually express CXCR5, PD-1, Bcl6, and SLAM and produce high levels of IL-21 after infection, TCRβ+CD1d-tetramer+ NKT cells do not upregulate Bcl6, CXCR5, or PD-1 and express moderate levels of SLAM and IL-21." (PMID 29249358, 2018). "Although L. monocytogenes-elicited γδ T cells appeared to share a similar anatomical niche as L. monocytogenes-specific CD4+ and CD8+ αβ T cells, all populations expanded robustly after infection and were maintained without any apparent competition for limiting resources or anatomic space." (PMID 30538697, 2018). "These cytokine levels, in combination with a lack of Foxp3 induction on CD4+CD25+ T cells, indicated that H. polygyrus induced a regulatory immune response in the EAE mice, which has been previously reported for H. polygyrus single infection." (PMID 28975357, 2018). "Unlike HIV infection, in which CD4+ T cells are directly infected, both CD4+ and CD8+ T cells remain refractory to direct infection by EBOV; however, the absolute number of T lymphocytes in peripheral blood perceptibly drops, particularly in patients who succumb to EVD." (PMID 29649305, 2018). "Moreover, it was shown that the antigen-specific IL-2+CD4+ T cell subsets were negative for KLRG1, which is a surface marker of terminally differentiated T cells, during Mtb challenge infection." (PMID 30123219, 2018). "Together, these data suggest that infection-induced NK1.1-expressing CD4+ T cells are not type I or II NKT cells but are instead a subset of conventional MHC-II-restricted CD4+ T cells, hereafter referred to as NK1.1+ CD4+ T cells." (PMID 30374346, 2018). "Naïve CD4+ T cells were stimulated with syngeneic DCNP30 collected from NP30‐immunized mice sacrificed at 0 (normal group were not infected with cercariae), 4 or 7 weeks after infection." (PMID 29577333, 2018). "By further characterizing antiviral CD4 T cells in the absence of IL-27R signaling, we demonstrated a dramatic increase in the proportion of cells expressing KLRG1 that was maintained throughout the course of infection." (PMID 30044874, 2018). "With regards to the liver, hepatic macrophages do not support viral replication in vivo and also express low levels of CD4 and co-receptors, CCR5/CXCR4, suggesting they may not be permissive to infection." (PMID 29466439, 2018). "It is not clear at this point how “rapamycin-primed” CD4+ and/or CD8+ T cells may participate in anti-Leishmania immunity in our model infection." (PMID 30133440, 2018). "Unfortunately, without monoclonal antibodies to identify CD4+ or CD8+ cells by flow cytometry, it is difficult to determine whether T cells are expanding in response to infection." (PMID 28959737, 2017).
infection (continued). "Only the animals depleted of CD4+ T-cells during vaccination and those that were vaccinated with rVSV expressing the Marburgvirus glycoprotein (rVSV-MARV; negative controls) succumbed to infection." (PMID 28428619, 2017). "We first clarified whether PHF13 is expressed in non-infected cell lines relevant for production and infection of HIV-1 as well as primary target cells (i.e. PBMC, CD4+ T cells and macrophages)." (PMID 29021215, 2017). "Although we have not studied the memory response in the infection model here, we also found a significant lower percentage of cells expressing high levels of the CD44 activation/memory marker among CD4+ T cells lacking IL-1R expression, as well as among Myd88−/− and Il18r1−/−CD4+ T cells." (PMID 28895840, 2017). "However, there is also evidence that a pool of long-lasting central memory CD4+ T cells (TCM) can develop in absence of persisting parasites, and that these can acquire effector functions after re-infection leading to protection." (PMID 29167671, 2017). "Two recent reports that studied the behavior of T cells and DCs in the intact LN after infection with non-replicating viruses showed that the Ag was first transported by migratory DCs to the LNs, but the initial clustering of CD8+ and CD4+ T cells occurred on different DC subsets." (PMID 28686740, 2017). "This hypothesis is supported by in vivo studies conducted in non-human primates, in which CD4+ T cell infiltrates became apparent only at day 4 post-infection with SIV, or later on during infection." (PMID 28542587, 2017). "In the absence of either CD4 or CD8 T cells, D2B6F1 mice survived Cl-13 infection." (PMID 28715493, 2017). "Infections were performed in the presence or absence of Prevotella stercorea, a gut microbe enriched in the mucosa of HIV-1-infected individuals that enhanced both TF HIV-1 replication and CD4+ T cell death ex vivo." (PMID 28241075, 2017). "CD4+ and CD4+/CD8+ T cell levels were significantly lower and CD8+ T cell levels were significantly greater in SLE patients with infection than in SLE patients without infection." (PMID 29267496, 2017). "Prior to infection, there was no significant increase in CD69 expression following TCR stimulation for both CD38+ and CD38- CD4+ T cells, although the basal expression of CD69 was higher on CD38+ CD4+ T cells." (PMID 27662621, 2016). "No integration was detected after infection of CCL19-treated resting CD4+ T cells with NL4-3 ΔNF-κB1 or ΔNF-κB1,B2, highlighting the critical role of the first NF-κB site in facilitating HIV integration in CCL19-treated resting CD4+ T cells." (PMID 27459960, 2016). "Apart from their role in activating T cells through antigen presentation, DCs are also thought to capture and directly transfer HIV to T cells in the genital mucosa by trans-infection, whereby they are not directly infected with HIV but transfer HIV to CD4 T cells for infection." (PMID 27171482, 2016). "Finally, we examined the molecular pathways responsible for instruction and/or maintenance of IL-10 expression by parasite-specific CD4+ IFN-γ+ T cells in the different lymphoid and nonlymphoid compartments during infection." (PMID 26459508, 2016). "On the other hand, adoptive transfer of CD4+ Foxp3+ T cells from mice stimulated with T. cruzi-exposed BMDC was able to reproduce the suppression of OTI CD8+ T cell priming in vivo, in absence of infection." (PMID 27332899, 2016). "Indeed, within 24 h of infection with Y. enterocolitica, there was a significant increase in the proportion of neonatal CD8+ cells while percentages of neonatal CD4+ and adult CD4+ and CD8+ did not increase." (PMID 28119902, 2016). "Indeed, it would be unexpected for Ag-experienced, including parasite-specific, memory CD4+ T cells to continue to produce IL-10, or any nonhomeostatic cytokine, in the absence of inflammation and TCR signals after infection." (PMID 27630165, 2016).
infection (continued). "At 4 and 9 weeks post-challenge, increased levels of triple-positive CD4+ T cells (co-expressing IFN-γ, TNF-α and IL-2), but not CD8+ T cells, were observed in the spleens and lungs of the Rv3628-immunized group compared with the infection control group." (PMID 27097115, 2016). "The bacteria were generally not detectable in the organs from non-infected animals that received either immune CD4+ or CD8+ T cells, excluding that a possible co-transfer of low amounts of contaminating R. typhi might have contributed to infection." (PMID 27875529, 2016). "However, no statistical differences were found between the total numbers of macrophages, dendritic cells, eosinophils, total CD4+ and CD8+ T cells, Th17 cells, and Treg cells for KN99α and cda1Δ2Δ3Δ mutant infection at each time point (data not shown)." (PMID 27165801, 2016). "Moreover, the surface expression of CD45RBlow on CD4+ and CD8+ T cells correlated with the absence of morbidity upon i.c. infection with DENV." (PMID 27631083, 2016). "Here we show that P. vivax blood-stage infection elicited a substantially different type of immune response compared to P. falciparum, with significant changes in the CD8+ T cell compartment rather than in the CD4+ T cell compartment." (PMID 27930660, 2016). "above) remained negative with all applied antibodies (including CD8, CD20, CD30, CD4, CD79), suggesting that these cells are not of lymphoid origin but could have undergone a progressive cellular shrinkage upon infection." (PMID 26803467, 2016). "Upon infection, CD8+, but not CD4+ cells, increased rapidly in proportion and IFNγ production." (PMID 28119902, 2016). "Activated Th1 CD4 T cells and effector CD8 T cells express this receptor, and promote migration of activated CD8 T cells into non-lymphoid tissue infection sites under the influence of the chemokine ligands CXCL9 and CXCL10." (PMID 26322025, 2015). "Notably, reconstitution of Rag1-/- mice with CD4+, but not CD8+ T cells largely restored the IEC hyper-proliferative response during infection." (PMID 26285214, 2015). "However, additional studies showed that mice lacking both CD4+ and CD8+ T cell subsets succumbed to infection." (PMID 25785602, 2015). "Although we demonstrated in our study that CD8+ Ag85A responses were unable to control the on-going infection, it may be possible that other antigens not contained within the vaccine will act protectively via CD8+ or CD4+ T-cells." (PMID 25996375, 2015). "Thus, another important finding of this study is that, in the absence of IL-27 signaling, CD4+ T cells mediated mortality directly through their secretion of IFN-γ, at least, during infection with extracellular protozoan parasites African trypanosomes." (PMID 26222157, 2015). "This is not surprising since HIV binding may involve multiple receptors and molecules (CD4, lectins like DC-SIGN and Siglec/CD169, heparan sulfate, etc....) and does not necessarily lead to productive infection." (PMID 25582927, 2015). "CD4+ T cell responses are essential for neutralizing antibody production, but data on the functionalities of TBEV-specific CD4+ T cells in response to vaccination or infection are lacking." (PMID 26465323, 2015). "It has also been reported that CD4+ T cells contribute to controlling MCMV in mice depleted of CD8+ T cells, but viral clearance is significantly delayed in most tissues and is never cleared from the salivary glands where a persistent infection develops." (PMID 24872114, 2014). "On the other hand, it is important to note that the follow up period for the experiments was only about one year and that CD4 T-cell decline and disease in the absence of CD8 T-cell depletion may require infections of longer durations." (PMID 25256394, 2014). "Because WT and CD25+/− CD4 cells showed only a 2-fold difference in cell numbers in the lung, we compared Ova specific responses in WT and CD25+/− effectors, but not CD25−/− effectors after PR8/Ova infection." (PMID 24586481, 2014).
infection (continued). "However, they had both total and specific CD8+ T-cells at the same level as patients with no infection or self-resolving infection, as well as the nine patients controlling infection with CD8+ T-cells alone before the appearance of specific CD4+ T-cells." (PMID 25166270, 2014). "While T-regs are known to be responsible for controlling the magnitude of CD4+ and CD8+ T-cell responses to viral infections, whether the accumulated T-regs in the elderly lead to impairment of host control of infection is not known." (PMID 25275464, 2014). "Influenza specific CD4 cells isolated from the lung, but not the draining lymph node (DLN), at 7 days post infection (dpi) expressed GrB and could lyse peptide coated targets directly ex vivo in a Prf dependent manner." (PMID 24586481, 2014). "Although the absolute numbers of all cell types analyzed considerably increased upon infection, we did not observe any change in relative numbers of CD8+ or CD4+ T lymphocytes, even though there were minor shifts in their CD44 and CD62L expressing subpopulations." (PMID 25919005, 2014). "Also HSV-1 specific CD4+ T cells are engaged in HSV-1 clearance from dorsal root ganglions possibly via nonlytic mechanism and local control of infection." (PMID 25276842, 2014). "This resolving infection has multiple IFN-γ-mediated acute and chronic effects on BM progenitors, and during the first week of infection IFN-γ is produced by myeloid, NK, NKT, CD4+ T cells, and some lineage-negative cells." (PMID 24825601, 2014). "On the other hand, we did observe efficient down-modulation of CD4 surface expression in resting T cells as well as Class I MHC down-modulation (unpublished data), but neither of their mRNA levels were affected by infection." (PMID 25330112, 2014). "In agreement with the lack of in vivo expansion following SIVsmE660 infection, SERV-K Env-specific CD4+ T cells failed to recognize SIV-infected macrophage targets and SERV-K Env-specific CD8+ T cells failed to recognize SIV-infected CD4+ T cell targets as measured by cytokine secretion." (PMID 24651676, 2014). "To examine whether the binding to CD4 and gp120 was required for the anti-HIV activity of HD5, we determined the effect of HD5 on infection by HIV-1 pseudotyped with VSV G envelope independent of HIV receptor and co-receptors for viral entry." (PMID 24086683, 2013). "Serum antibody levels and CD8 T cell infiltration into the CNS was unaltered at early time points, but both were impaired in the absence of CD4 T cells at late time points, suggesting CD4 T cells contribute to control of WNV by providing help to B cells and CD8 T cells at late stages of infection." (PMID 24153060, 2013). "Moreover, γδ+ T cells impaired the transfer of protection by Socs3fl/fl lck cre CD4+T cells, suggesting that SOCS3 inhibits a non-redundant detrimental role of γδ+ T cells in the outcome of infection with M. tuberculosis." (PMID 23853585, 2013). "Infection with either SIV-rtTAΔnef or SIVΔnef induced α4+β7+ CD4+CD95+ and CD8+CD95+ TCM and TEM subsets although the change in CD4+ TEM cells failed to reach statistical significance the result was skewed by macaque E67, which also was an exception in the CD8+ TEM population." (PMID 23738926, 2013). "Conversely, in the nonpathogenic infection of AGMs, a low expression of CCR5 by the mDCs recapitulates previous reports in this species documenting a similar low CCR5 expression by CD4+ T cells and suggests a reduced mDC migration to the intestine in this animal model." (PMID 24098110, 2013). "Interestingly, at six weeks post infection in the lungs, there was also a negative correlation between IFN-γ+TNF-α+IL-2+ and IFN-γ+TNF-α+ CD4 T cells and bacteria levels." (PMID 23977248, 2013). "Furthermore, at days 28 and 42 post infection, B6.CCR7-/- mice have a higher percentage of cells expressing IL-4, which was also seen in the CD4+ compartment but not by CD8+ T cells." (PMID 24205367, 2013).
infection (continued). "Notably, most (≥ 70%) of CD4+ and CD8+ T cells exhibited an activated phenotype (CD62L-negative) in the liver, but not in the spleen, irrespective of the infection." (PMID 24358216, 2013). "Unexpectedly, LCMV Clone 13 infection was not controlled in Il-10fl/flxCD11c-Cre+ mice and resulted in low percentages and total numbers of TNF-α producing antiviral CD8+ and CD4+ T cells comparable to littermate and C57BL/6 controls." (PMID 24244162, 2013). "Taken together, our data showed that the adjuvanted subunit and MVA strategies led to different T cell subset combinations pre and post infection and that TNF-α/IL-2 double producing but not IFN-γ single producing CD4 T cell subsets correlated with protection in the mouse TB model." (PMID 23977248, 2013). "Additionally, associated with each sequence are clinical covariates such as CD4 counts, last negative test dates, and BED test results that are informative about the stage of infection at the time of diagnosis." (PMID 24367249, 2013). "Finally, we tested the effect of the absence of CD4- and/or CD8-positive cells during immunization and challenge infection (Depletion-C)." (PMID 24376753, 2013). "Following semi-random integration into the genome of host CD4+ T cells, HIV usually establishes a productive infection, but in rare cases can adopt a non-replicating but reversible latent phenotype, such as when an infected activated T cell transitions to a memory T cell." (PMID 23874178, 2013). "Together, these data suggest that during infection the LN feed arteriole has decreased NOS activity contributing to vessel diameter three and five days p.i. and that this reduction, unlike the mechanism of remodeling, is not dependent upon CD4+ T cells." (PMID 23573281, 2013). "Seminal studies on experimental infections of Leishmania major in C57BL/6 and BALB/c inbred mouse strains correlated parasite control with the elaboration of interferon gamma (IFN-γ) by CD4+ T cells and uncontrolled infections with the absence of IFN-γ in the C57BL/6 and BALB/c mice, respectively." (PMID 23801993, 2013). "The influence on other immune cells such as NK, B, CD4+, and CD8+ cells on days 2 and 4 after infection was not so clear in mice treated with etanercept, and so more-detailed future studies will be performed at day 7 (and later) after infection to clarify this observation." (PMID 24373231, 2013). "We set out to test the scenario of selection for CD4 tropism in the absence of immune pressure, by long term culturing in normal hPBMCs of two SIV strains which exhibit CD4 independence during initial rounds of infection in hPBMCs." (PMID 22830620, 2012). "We also observed that CD8+ T cells from HIV un-infected individuals do not suppress autologous in vitro infected CD4+ T cells even in the presence of Tim-3 blocking antibodies, further indicating the indispensible role of TCR engagement by antigen in infection suppression." (PMID 22792231, 2012). "Patient groups were similar in their CD4+ response to nonparasite antigen but strongly differed in their CD8+ responses, demonstrating the potential global ramifications of chronic, longstanding infection." (PMID 22389737, 2012). "Interestingly, inhibition of CCR6 and CXCR3 chemokine receptors, which are proposed to be important in gut homing by T cells and are the most abundant chemokine receptors expressed by CD4+ T cells in the MLN, did not prevent expulsion of infection." (PMID 23053395, 2012). "This indicates that MHC class I and class II antigen presentation pathways were sufficiently functional after VACV-GP-infection irrespective of ageing, Tx and latent MCMV-infection to allow comparable expansion of naïve TCR-tg CD4+ and CD8+ T cell populations." (PMID 22916013, 2012). "Furthermore, the NP311–325 specific CD4 T cell response in the TSLPR−/− compartment also showed no impairment, consistent with direct infection of TSLPR−/− mice." (PMID 23189186, 2012).